SLC38A10 (solute carrier family 38 member 10)
Description:
Facilitates bidirectional transport of amino acids. May act as a glutamate sensor that regulates glutamate-glutamine cycle and mTOR signaling in the brain. The transport mechanism remains to be elucidated.
Synonyms: PP1744; MGC15523; SNAT10
Tractability: Antibody: UniProt predicts a signal peptide or a membrane-spanning region. PROTAC: ubiquitination databases record sites on it; its protein half-life has been measured.
Gene: Protein-coding gene on chromosome 17 (81,244,811 to 81,295,567, reverse strand). Ensembl gene ENSG00000157637.
Subcellular location: Membrane
Subcellular location (Human Protein Atlas): Golgi apparatus
Gene Ontology:
Molecular function: L-amino acid transmembrane transporter activity
Biological process: amino acid transmembrane transport; L-alpha-amino acid transmembrane transport
Cellular component: Golgi apparatus; membrane
Genetic constraint (gnomAD): Loss-of-function variants: 51 observed, 76.62 expected, observed/expected ratio (o/e) 0.67, 90% interval 0.53 to 0.84. The upper end of that interval is the gene's LOEUF score, 0.84, which puts it in group 3 of 6, group 1 being the genes least tolerant of losing a copy. Missense variants: 1,405 observed, 1,428.4 expected, observed/expected ratio (o/e) 0.98, 90% interval 0.94 to 1.03. Synonymous variants: 637 observed, 609.58 expected, observed/expected ratio (o/e) 1.04, 90% interval 0.98 to 1.12.
Homologues: Orthologues: chimpanzee SLC38A10 (99% identical), macaque SLC38A10 (95% identical), guinea pig SLC38A10 (73% identical), dog SLC38A10 (72% identical), rat Slc38a10 (69% identical), pig SLC38A10 (68% identical), mouse Slc38a10 (68% identical), tropical clawed frog slc38a10 (46% identical), zebrafish slc38a10 (42% identical), Drosophila melanogaster CG30394 (19% identical), Caenorhabditis elegans Y51F10.4 (14% identical). Paralogues in human: SLC38A2 (11% identical), SLC38A3 (10% identical), SLC38A4 (10% identical), SLC38A5 (9% identical), SLC38A1 (9% identical), SLC38A6 (9% identical), SLC38A11 (8% identical), SLC36A2 (8% identical), SLC38A8 (7% identical), SLC36A1 (7% identical), SLC36A3 (7% identical), SLC38A7 (7% identical), and 3 more.
Diseases named in the same sentence as SLC38A10 in open-access papers:
SLC38A10 is named in the same sentence as 17 diseases in open-access papers, as found by Europe PMC text mining. Sharing a sentence is not in itself a finding about the gene and the disease. The quoted sentences say what the papers report.
schizophrenia (4 papers, 2021 to 2022). A major psychotic disorder characterized by abnormalities in the perception or expression of reality. "SLC38A10 has also been found to be associated with Alzheimer’s disease, and a single-nucleotide polymorphism (SNP) and methylation differences in SLC38A10 have been associated with frontotemporal dementia and schizophrenia." (PMID 36620864, 2022). "It was suggested that SLC38A10 plays a vital role in the regulation of neurotransmission, and polymorphisms in SLC38A10 are associated with autism spectrum disorders, bipolar disorder, schizophrenia, and Alzheimer disorder in human." (PMID 34026845, 2021). "Furthermore, genetic mutation of SLC38A10 has been found to be associated with schizophrenia and bipolar disorder." (PMID 35450293, 2022).
cholangiocarcinoma (1 paper, 2021). A carcinoma that arises from the intrahepatic biliary tree (intrahepatic cholangiocarcinoma) or from the junction, or adjacent to the junction, of the right and left hepatic ducts (hilar cholangiocarcinoma). "Finally, six AS events, SLC38A10-44114-AT, IL18BP-17488-RI, NBPF10-5531-ES, THNSL2-54469-ME, FAM3A-90629-ES, and KIAA1432-85794-AT, were identified as independent risk factors for OS in cholangiocarcinoma." (PMID 34055632, 2021).
Insulin resistance (1 paper, 2019). Increased resistance towards insulin, that is, diminished effectiveness of insulin in reducing blood glucose levels. "Solute carrier family 38, member 10 (SLC38A10), SYNC, and DMRT3 are novel biomarkers for the development of insulin resistance." (PMID 30678306, 2019).
migraines (1 paper, 2025). "Burden testing identified several genes, including GCOM1, SETX, and SLC38A10, as significantly associated with HM, many of which have known roles in neurological function or migraine-related pathways." (PMID 40725463, 2025). "Variants that disrupt the function of this transporter may consequently influence an individual’s predisposition to migraines, underscoring the need for further research into the role of SLC38A10 in HM pathogenesis." (PMID 40725463, 2025). "The SLC38A10 gene, which transports glutamate in a manner that confers protection against stress and glutamate toxicity, is, therefore, a critical component in modulating migraine susceptibility." (PMID 40725463, 2025).
osteogenesis imperfecta (1 paper, 2012). Osteogenesis imperfecta (OI) comprises a heterogeneous group of genetic disorders characterized by increased bone fragility, low bone mass, and susceptibility to bone fractures with variable severity. "Disorders of bone matrix as typified by osteogenesis imperfecta are characterized by bone that is weak and brittle with low BMC, and three of the strains (Prpsap2, Slc38a10, Sparc) displayed this phenotype." (PMID 22876197, 2012).
ovarian carcinoma (1 paper, 2022). A malignant neoplasm originating from the surface ovarian epithelium. "A study investigating the role of solute carrier family of membrane transporters in ovarian cancer revealed the down-regulation of SLC38A10 in ovarian cancer tissues when compared to normal ovarian tissues." (PMID 36338962, 2022).
pancreatic cancer (1 paper, 2023). "Based on the protein expression profiles of pancreatic cancer samples collected in the Human Protein Atlas (HPA) database, LDHA, GLS2, and SLC38A10 exhibited higher expression levels in pancreatic cancer." (PMID 37333498, 2023). "In the current study, a total of 17 genes with prognostic values have been identified, of which 8 genes (SFXN5, LRRC8E, KCNJ10, UPB1, SLC43A2, SLC38A10, ACCS, and SLC38A5) were identified for the first time in pancreatic cancer." (PMID 37333498, 2023).
tumor (2 papers, 2022 to 2023). "By analyzing TCGA data in the GEPIA database, we found that the expression levels of multiple SLC38A family members (including SLC38A2, SLC38A4, SLC38A5, SLC38A6, SLC38A7, SLC38A8, SLC38A9, and SLC38A10) were significantly upregulated in GC tumor tissues." (PMID 36918802, 2023).
cancer (1 paper, 2020). A tumor composed of atypical neoplastic, often pleomorphic cells that invade other tissues. "Several other genes residing at the association loci reported include known drug targets with repurposing opportunities, such as GRK6, CD44, SLC38A10, and ADK, with potential implications across multiple different cancers and auto-inflammatory diseases." (PMID 31937769, 2020).
neurodegenerative disease (1 paper, 2022). A disorder of the central nervous system characterized by gradual and progressive loss of neural tissue and neurologic function. "This possible underlying mechanism suggests a principal role of SLC38A10 in brain glutamate metabolism and neurodegenerative diseases." (PMID 35450293, 2022). "In conclusion, the SLC38A10 knockout model revealed the new finding of SLC38A10 in glutamate metabolism, mTOR dependent protein and fatty acid regulation, supporting a previous association between SLC38A10 polymorphisms and neurodegenerative diseases." (PMID 35450293, 2022).
Neurological Disease (1 paper, 2022). "Results from disease and molecular function indicated an increased sensitivity to neurological diseases in KO due to an absence of SLC38A10." (PMID 35450293, 2022).
SLC38A10 also shares sentences with these, for which no sentence is quoted: Alzheimer disease (2 papers); bipolar disorder (2); frontotemporal dementia (2); autism spectrum disorder (1); Autoimmunity (1); multiple sclerosis (1).